AQP4 (aquaporin 4)
Diseases named in the same sentence as AQP4 in open-access papers (continued):
Sharing a sentence is not in itself a finding about the gene and the disease.
glioma (continued). "Interestingly, TAMs express VEGF, IL-1, MMPs, or AQP4, which are all implicated in the pathogenesis of glioma-related edema." (PMID 35910247, 2022). "However, gliomas are associated with aberrant spatial expression of astrocytic AQP4 and AQP4 redistribution across the glioma cell surface." (PMID 35910247, 2022). "A recent studysuggested that loss of AQP4 assembly into OAPs may facilitate evasion ofapoptosis and enhanced migration in glioma cells, but how this interacts withtumour-associated oedema or AQP4 localization remains unexplored." (PMID 34499128, 2022). "Interestingly, AQP4 upregulation in gliomas versus normal brain tissues has been mainly associated with glioma-associated blood-brain barrier disturbance and PTBE." (PMID 33538957, 2021). "This loss of AQP4 polarity may contribute to increased migration capability of the astrocytoma cells, as AQP4 aggregation state has been shown to have an effect on glioma cell migration." (PMID 32111087, 2020). "Additionally, aquaporin-4 (AQP4), a highly regulated water channel protein in the central nervous system, has been linked to high-grade gliomas as well." (PMID 32160197, 2020). "However, opposing evidence showed knockdown of AQP4 in primary human astrocytes correlated with down-regulation of connexin-43; and transfection of wild type AQP4 into glioma cell lines caused enhanced adhesion." (PMID 29922644, 2018). "Other authors have associated AQP4 with the regulation of human glioma cell migration and invasion." (PMID 28423683, 2017). "The AQP4 arrangement through the membrane contributes to edema resolution and it is believed that the upregulation of AQP4 observed in gliomas in vivo is a mechanism of compensation for the loss of the endfeet and the increase in the perivascular space observed in gliomas." (PMID 25565956, 2014). "Therefore, an abnormal expression and localization of AQP4 may exist in glioma and form part of the mechanism underlying the generation of clinical symptoms." (PMID 40243478, 2025). "Notably, AQP-4 is implicated in glioma cell motility and invasion, and its downregulation may indicate attenuation of malignancy-related traits." (PMID 41154863, 2025). "Furthermore, the subcellular redistribution of AQP4 in glioma might be caused by modification after translation." (PMID 39247976, 2024). "Simultaneous inhibition of AQP4 and co-expressed ion channels has shown synergistic effects in reducing glioma cell viability." (PMID 41324079, 2025). "The overexpression of AQP-4 channels in gliomas appears to restrict fluid flow, leading to peritumoral edema." (PMID 40464180, 2025). "By orchestrating both glioma cell motility and immune evasion, AQP4 emerges as a dual-threat molecule within the GBM microenvironment." (PMID 41324079, 2025). "In the present study, we confirmed that AQP4 was upregulated in proliferating glioma cells and explains the strong correlation between MRI-kio and histology-Ki67+." (PMID 40225573, 2025). "Animal models provide corroborating evidence; in a rat glioma model, the implanted tumor was shown to block the arterial perivascular influx pathway and downregulate AQP4 expression, resulting in diminished glymphatic tracer transport." (PMID 41510293, 2025). "AQP4-KO significantly reduced Ki67 positivity (Ki67+) in rat glioma models (4.4 ± 1.5% Vs 19.9 ± 3.8% p = 0.0007, n = 11, 9)." (PMID 40225573, 2025). "Another study demonstrated that targeted inhibition of AQP4 alleviated radiation-induced lung injury and suppressed M2 macrophage activation; however, similar studies in gliomas remain limited." (PMID 40788933, 2025). "Recent single-cell RNA sequencing studies further support this relationship by demonstrating shifts in macrophage polarization states in AQP4-high gliomas." (PMID 41324079, 2025). "Beyond its role in water transport, AQP4 contributes to glioma cell migration and invasion through dynamic cytoskeletal remodeling, membrane plasticity, and interactions with ion channels." (PMID 41324079, 2025).
glioma (continued). "We propose a refined anatomical model of the glymphatic system, including four functional zones, and evaluate the isoform-specific contributions of AQP4 to glioma cell behavior." (PMID 41324079, 2025). "AQP4-enriched astrocytic domains in gliomas often co-localize with regions exhibiting poor therapeutic penetration, hinting at a protective spatial arrangement that shelters vulnerable glioma subpopulations." (PMID 41324079, 2025). "Pharmacologic inhibition of AQP4—alone or in combination with ion channel modulators—has shown promise in preclinical models by reducing glioma cell motility, sensitizing tumors to standard therapies, and suppressing recurrence." (PMID 41324079, 2025). "In bulk RNA sequencing and proteomic analyses across various cancer types, AQP4 consistently shows higher expression at both the mRNA and protein levels in glioma tissues compared to normal tissues." (PMID 40788933, 2025). "The mechanism that underlies the potential for kio to serve as a direct and accurate biomarker for Ki67 involves the upregulation of AQP4 expression during glioma cell proliferation." (PMID 40225573, 2025). "To validate the involvement of AQP4 as a crucial molecule in regulating glioma proliferation, we created an AQP4-KO C6 cell line using a small guide RNA (sgRNA)." (PMID 40225573, 2025). "In AQP4+ glioma cells, the percentage of Ki67+ cells were also significantly greater than that of Ki67- cells (85.9% ± 1.8% vs 39.4% ± 2.6%, p < 0.0001, n = 60)." (PMID 40225573, 2025). "The authors of the study proposed the para-arterial influx of subarachnoid CSF to be decreased due to the AQP-4 dysfunction in glioma." (PMID 40464180, 2025). "It is evident that impairment of water homeostasis affects glioma advancement and AQP4 subcellular dislocation is one of the pathophysiological mechanisms driving glioblastoma." (PMID 39247976, 2024). "The present article offers an appropriate introduction to the potential involvement of AQP4 in the emergence and progression of glioma." (PMID 39247976, 2024). "AQP4 isoforms, known as M1 and M23, have been shown to change the aggregation/disaggregation state into orthogonal arrangements of particles (OAPs) and glioma cell survival." (PMID 38476871, 2024). "Several key studies have provided results that summarize the impact of AQP4 on encouraging glioma migration and invasion of cells." (PMID 39247976, 2024). "We used RNA-seq as a search strategy to identify the differential expression of AQP1 and AQP4 transcripts in glioma tissues data compared to normal brain tissues data." (PMID 38476871, 2024). "The quantitative analysis further confirmed a significantly higher occurrence of round-shaped cells in glioma cells expressing human AQP4-OAPs following treatment with zoledronic acid, as compared to untreated cells." (PMID 39200356, 2024). "The impact of AQP4 subcellular mislocalization on glioma progression and the precise mechanisms regarding AQP4 translocation in glioma need further investigation." (PMID 39247976, 2024). "Some endogenous factors such as hormonal and metabolic changes also modulate AQP4 expression in human gliomas." (PMID 38476871, 2024). "The AQP4 aggregation state similarly and significantly caused an upregulation of the KCNJ11, ABCC8, and ABCC9 genes in U87 glioma cells." (PMID 39200356, 2024). "In glioma, AQP4 protein expression is increased, and its inhibition can significantly inhibit the malignant proliferation of glioma." (PMID 39247976, 2024). "As expected, both AQP1 and AQP4 mRNAs were overexpressed in glioma samples (logFC = 1.42 x 10+14 and 1.02 x 10+14; P-value = 1.66E-40 and 8.82E-26, respectively) compared with the healthy brain samples." (PMID 38476871, 2024). "Among the glioma subtypes, AQP1 and AQP4 were overexpressed in astrocytoma (low-grade glioma) and classical (high-grade glioma)." (PMID 38476871, 2024).
glioma (continued). "In one of our previous investigations, we conducted a systematic analysis that described the key function of AQP4 in the malignant development of glioma." (PMID 39247976, 2024). "We used RNA-seq as an experimental strategy and identified the number of differential AQP1 and AQP4 transcript expressions in glioma tissue compared to normal brain tissue." (PMID 38476871, 2024). "Conversely, the expression of M1 AQP4-tetramers that are unable to aggregate into OAPs increased the invasiveness, cell migration, and metalloproteinase-9 activity of glioma cells escaping apoptosis." (PMID 39200356, 2024). "Water exchange through aquaporin-4 being measured by MRI, transmembrane water-efflux rates are a biomarker of proliferative glioma." (PMID 38803391, 2024). "Targeting AQP4 subcellular translocation to the cell surface is another approach that can be potentially used in glioma treatment." (PMID 39247976, 2024). "In this review, we update recent findings about disturbed AQP4 expression in glioma and explore targeting AQP4 to modulate the glioma progression." (PMID 39247976, 2024). "The upregulation of AQP4 expression in brain tumors has been proposed to modulate human glioma cell migration, cell invasion, and cerebral edema." (PMID 38263015, 2024). "All in all, in addition to its significance in water transport, AQP4 has possibly significant functions in the migration, invasion and regulation of gliomas." (PMID 39247976, 2024). "In this study, we aimed to identify the expression pattern of AQP1 and AQP4 genes in human gliomas, as well as to highlight their regulatory potential within the cancer microenvironment." (PMID 38476871, 2024). "Simone and coworkers demonstrated that the aggregation of AQP4 in OAPs influences the biology and the fate of glioma cells." (PMID 39200356, 2024). "They disclosed that AQP4-expression was greater in glioma than in normal tissue, and that increase in MMPs immunoreactivity was related to the loss of agrin and dystroglycan, correspondingly." (PMID 38336645, 2024). "* Tumor suppressor in glioma by targeting aquaporin 4, a gene highly expressed in gliomas and involved with glioma progression.* Inhibits c-Myc, acting on both cellular proliferation and invasion processes." (PMID 36936170, 2023). "By digging and comparing the heterogeneity of glioma cells based on the expression of AQP4, we investigated the correlation between AQP4 and the glioma immune microenvironment from a novel perspective." (PMID 36599974, 2023). "In gliomas, aquaporin 4 is highly concentrated at the cell membrane covering the surface of tumor cells and is strongly upregulated and redistributed across the surface of glioma cells." (PMID 37893105, 2023). "We suspect that AQP4 has the ability to indicate the polarization propensity of macrophages and thus the glioma immune microenvironment." (PMID 36599974, 2023). "Mouse models recapitulate the diverse roles of AQP4 in glioma-related brain edema, although the phenotypes produced in knockouts have been variable." (PMID 36768856, 2023). "Meanwhile, AQP4 affects the invasion and migration of glioma and is closely related to vasogenic edema and cytotoxic edema induced by glioma." (PMID 37280594, 2023). "The same result was observed in the TCGA glioma database, showing poor overall survival and poor response to chemotherapy in AQP4 overexpressed populations." (PMID 36599974, 2023). "The gene expression profile showed that AQP4 is highly expressed in gliomas (including GBM and LGG) than in normal brain tissues." (PMID 36599974, 2023). "As for immune-related aspects, there is little research regarding AQP4 and glioma’s immune system within the last ten years except for two case reports." (PMID 36599974, 2023). "Based on the dimensional reduction plot of tumor cells, we further examined the AQP4 expression among each glioma sample." (PMID 36599974, 2023).
glioma (continued). "It has been identified that alterations of the AQP4 aggregation state can influence plasma membrane dynamics, offering the potential for metastasis of glioma and changes of the tumor microenvironment." (PMID 36599974, 2023). "Our study then examined the immunological pattern of AQP4 in gliomas, as well we the potential prognostic value of the AQP4-related signatures in the response of commonly used drugs and drug resistance of chemotherapy in different databases." (PMID 36523816, 2022). "The suppression of AQP4 in a human breast cancer cell line model upregulated E- cadherin, whereas in glioma cells, it resulted in enhanced β-catenin and connexin 43 expression." (PMID 35847914, 2022). "In particular, numerous studies addressed the possible role of AQP4 in glioma-related edema, as well as in the regulation of glioma cell proliferation, invasivity, cell migration, and the brain glymphatic system." (PMID 35910247, 2022). "In conclusion, this study demonstrates that invasiveness or apoptosis traits of glioma cells expressing AQP4 protein affect the signal transferred to surrounding cells." (PMID 36071478, 2022). "Our previous research have also indicated the close involvement of AQP4 in glioma cell invasion and migration, as well as drug resistance." (PMID 36523816, 2022). "The study has been conducted using the most widespread experimental model of glioma: the U87 cell line as recipient cells and U87 cells transfected with AQP4–tetramers or AQP4-OAPs as donor cells, in serum withdrawal conditions." (PMID 36071478, 2022). "Our previous research has indicated that AQP4 exerted carcinogenic effects via various pathways in glioma." (PMID 36523816, 2022). "Tumor implantation experiments in AQP4-null mice have further solidified the role of AQP4 in the development of glioma." (PMID 35847914, 2022). "Recent studies have revealed the critical role of AQP4 in the occurrence and development of gliomas." (PMID 36523816, 2022). "As a result, the involvement of AQP4 in the immune regulation of glioma and the immunotherapy process was investigated further in this work." (PMID 36523816, 2022). "AQP4 expressing glioma cells showed significantly reduced invasion compared with AQP1 and S180 expressing tumors as determined by quantitative stereology, consistent with a differential role for AQP1 and AQP4 in this process." (PMID 35847914, 2022). "In gliomas, a redistributed expression of AQP4 was observed compared with normal central nervous system tissue." (PMID 35847914, 2022). "We have previously demonstrated the dual role of the glial water channel aquaporin-4 (AQP4) protein in glioma progression or suppression depending on its aggregation state." (PMID 36071478, 2022). "The expression of AQP4 protein in tumor samples from 77 glioma patients was evaluated by immunohistochemical (IHC) staining of a tissue microarray." (PMID 36523816, 2022). "In glioma, the expression of the AQP4 protein is elevated, and inhibiting AQP4 can significantly reduce glioma malignant proliferation." (PMID 36523816, 2022). "In bioinformatics analysis, we took the intersection of upregulated genes identified in TCGA-GBM dataset, TCGA-LGG dataset, and the GSE140746 microarray, four glioma-related candidate genes were thereupon obtained, namely AQP4, BIRCS, MAGT1, and MGP)." (PMID 35416125, 2022). "Currently the significant roles of AQP4 in combating drug resistance during glioma chemotherapy, as well as the potential AQP4 pharmacological blockers require additional research." (PMID 36523816, 2022). "In the present study, we demonstrate that glioma cells expressing AQP4 can export their metastatic or apoptotic phenotypes toward tumour surrounding cells, and this phenomenon is, at least in part, mediated by intercellular transfer of EVs." (PMID 36071478, 2022). "For the first time, current research has examined the role of AQP4 in the CNS immune system and find out how important it is in the glioma immunotherapy process." (PMID 36523816, 2022).
glioma (continued). "The preliminary analysis of protein released in extracellular space by glioma cells, either expressing AQP4-OAPs or AQP4–tetramers, confirms the presence of AQP4, suggesting that, apart from its role in cell physiology, AQP4 also exists as a secreted protein." (PMID 36071478, 2022). "Our earlier study systematically summarized the critical role of AQP4 in the malignant progression of glioma and its significance in the study of anti-tumor drug resistance." (PMID 36523816, 2022). "More importantly, we also found that AQP4 was highly expressed in glioma tissues and that the expression level of AQP4 was negatively correlated with the glioma grade (Spearman’s rank correlation rs = 0.297, p = 0.013)." (PMID 36523816, 2022). "In the present study we evaluated the AQP4-related immunological pattern in various cancers, especially glioma." (PMID 36523816, 2022). "A role for AQP4 in glioma cell migration was initially proposed to occur through the regulation of cell volume and cytoskeletal interactions." (PMID 35847914, 2022). "From the analysis of actin cytoskeleton we demonstrate that glioma cells expressing AQP4-OAPs show a higher density of actin rings and many F-actin-rich regions resembling vesicular structures completely coated in filamentous actin." (PMID 36071478, 2022). "Generally, AQP4-OAPs favor apoptotic glioma cell fate, while AQP4 tetramers increase glioma cell invasiveness." (PMID 35910247, 2022). "By EV-mediated crosstalk, the phenotypic features of donor cells are exported to receiving glioma cells, amplifying the role of AQP4 in glioma cells also in surrounding cells." (PMID 36071478, 2022). "The results indicated that low AQP4 expression was significantly correlated with lower clinical grade glioma (grade 1/2), while high AQP4 expression predicted higher clinical grade glioma (grade 3/4) in patients (X 2 = 12.434, p < 0.001)." (PMID 36523816, 2022). "In experiments using glioma cell lines and a primary astrocyte model, reduced expression of AQP4 was shown to result in reduced cell migration and compromised F-actin formation." (PMID 35847914, 2022). "In detail, large EVs derived from more invading glioma cells expressing AQP4-tetramers potentiate the migratory response of receiving glioma cells, while EVs shed by apoptotic glioma cells expressing AQP4-OAPs favour the apoptotic path of receiving cells." (PMID 36071478, 2022). "More importantly, we anticipate developing an AQP4-related prognostic model, which would serve as a critical theoretical research foundation for improving the effect of glioma immunotherapy." (PMID 36523816, 2022). "More importantly, we anticipated developing an AQP4-related prognostic model, which would serve as a critical theoretical research foundation for improving the effect of glioma immunotherapy." (PMID 36523816, 2022). "This study aimed to examine the role of AQP4 in the CNS immune system and find out how important it is in the glioma immunotherapy process." (PMID 36523816, 2022). "PKC-mediated phosphorylation of AQP4 at serine 180 correlated with a decreased glioma cell invasion." (PMID 35847914, 2022). "In glioma followed by the vasogenic brain edema model, AQP4-null mice showed a significantly greater increase in water in the brain and intracranial pressure (ICP) than that in wild-type mice." (PMID 35083148, 2021). "Future assessments on the relationship between AQP4 and apoptosis are required in hope of establishing a novel target for pharmacological approaches in the treatment of glioma and other CNS disorders." (PMID 34267610, 2021). "In this study, we found that glioma blocked the arterial perivascular space pathway of the glymphatic system and specifically reduced the key protein, AQP4." (PMID 35083148, 2021). "This study focused on changes in the glymphatic system and the role of aquaporin 4 (AQP4) in glymphatic transport in glioma." (PMID 35083148, 2021).